ERBB2 (erb-b2 receptor tyrosine kinase 2)
Diseases named in the same sentence as ERBB2 in open-access papers (continued):
Sharing a sentence is not in itself a finding about the gene and the disease.
breast tumors (continued). "Results of our observations proved the ERBB2 amplification in breast tumors by the appliance of the MLPA technique." (PMID 29743853, 2018). "ErbB2/Her2 oncoprotein is often overproduced by breast tumor cells and blocks their anoikis by partially understood mechanisms." (PMID 30545388, 2018). "We then characterized the breast tumors according to the four major molecular subgroups, i.e., luminal A (n = 216), luminal B (n = 121), ERBB2 (n = 44), and triple-negative tumors (n = 67)." (PMID 30285739, 2018). "Here, we show that in vivo treatment of ErbB2-positive breast tumor xenografts with GroA reduces tumor size and leads to decreased ErbB2-mediated signaling." (PMID 29352243, 2018). "We observed that trastuzumab and lapatinib upregulate Irf6 in ErbB2-positive human breast tumor cells and that neoadjuvant trastuzumab-based therapies tend to upregulate Irf6 in human breast tumors." (PMID 30545388, 2018). "Fifteen to twenty percent of breast tumors overproduce ErbB2/Her2 receptor tyrosine kinase, which drives these cancers." (PMID 30545388, 2018). "Our results show that palindromic gene amplification, likely resulting from BFB cycles, is a predominant mechanism driving ERBB2 oncogene amplification in HER2-positive breast tumors." (PMID 28211519, 2017). "This novel integrated imaging strategy is promising for visualizing ErbB2 expression in breast tumors and serve as an adjunct during surgery to improve diagnostic accuracy, identify tumor margins, and stage early cancers." (PMID 29089571, 2017). "In summary, our data indicate that Mek blocks lysosomal ErbB2 degradation in detached breast tumor cells." (PMID 29285258, 2017). "The authors reported that loss of RCP leads to the downregulation of E-cadherin and increased metastatic potential of ErbB2 positive breast tumours." (PMID 29285208, 2017). "Altogether, these data highlight the potential clinical impact of p140Cap expression and of p140Cap-regulated pathways in human ERBB2 breast tumours as new therapeutic targets." (PMID 28300085, 2017). "The mRNA levels of ERalpha, ERbeta, epidermal growth factor receptor, ErbB2, ErbB3, ErbB4, ERRα, ERRβ, and ERRγ were determined in unselected primary breast tumors and normal mammary epithelial cells enriched from reduction mammoplasties." (PMID 28945747, 2017). "Amplification of a genomic region on chromosome 17q12 containing the HER2/ERBB2 gene, a member of the ERBB receptor family, has been observed in about 25% of breast tumors and this is associated with aggressive disease and lower survival of patients." (PMID 29212182, 2017). "We had also previously observed an inverse correlation between IRF9 and ErbB2 expression in a panel of breast tumor cell lines." (PMID 28174229, 2017). "We aim to demonstrate real-time optical sectioning using a near-infrared labeled ErbB2 peptide that generates tumor-specific contrast in human xenograft breast tumors in vivo." (PMID 29089571, 2017). "Breast tumours overexpressing ErbB2 show a significant response to ErbB2 targeting agents such as trastuzumab or lapatinib." (PMID 28417948, 2017). "The amplification mechanism of ERBB2 is a critical missing piece of information for the better understanding of the biology of HER2-positive breast tumors." (PMID 28211519, 2017). "In summary, we have developed a NIR-labeled peptide to detect in vivo ErbB2 expressed microscopically in human breast tumors using a miniature dual-axes confocal fluorescence endomicroscope to support future image-guided surgery." (PMID 29089571, 2017). "Another antibody against ErbB2, pertuzumab, has been developed to treat HER2+ breast tumor in combination with trastuzumab." (PMID 28338617, 2017). "We measured the extent to which the transcriptomes of breast tumors with amplifications of ERBB2, MYC or CCND1 oncogenes are due to the accompanying onco-passenger CNVs." (PMID 29069713, 2017).
breast tumors (continued). "Taken together, there was a strong co-occurrence between copy number increase and palindromic DNA within the ERBB2 region in HER2-positive breast tumors." (PMID 28211519, 2017). "With these mechanistic insights, we propose a model in which BFB cycles give rise to ERBB2 amplification in HER2-positive breast tumors." (PMID 28211519, 2017). "The expression of ERBB2 is inversely correlated with the level of miR-155 (a well-documented oncogenic miRNA) in ERBB2-positive breast tumors." (PMID 28160563, 2017). "15-20% of breast tumors overproduce ErbB2/Her2 oncoprotein which drives the progression of these malignancies." (PMID 29285258, 2017). "One critical feature of primary and disseminated breast tumors, including those overproducing ErbB2, is their ability to grow in a three-dimensional manner." (PMID 29285258, 2017). "In rank order the MNAI was lowest in normal-like tumors and luminal-A tumors, with progressively increasing MNAI values for luminal-B tumors, ERBB2-positive tumors and basal-like breast tumors (82 % of basal-like tumors exhibited high MNAI)." (PMID 27368372, 2016). "Nevertheless, an effective treatment of ErbB2-overexpressing breast tumours necessitates strategies that not only rely on rapid induction of cell death, but also counter the tumour escape mechanisms leading to a long-term adaptation to the treatment." (PMID 27255951, 2016). "Analysis of a set of 402 breast tumours showed that TOM1L1 was the most frequently co-amplified gene with ERBB2 in the 17q22-q23 region." (PMID 26899482, 2016). "Compared with trastuzumab plus pertuzumab, the combination of trastuzumab, pertuzumab and 3E10 provides a more potent blockade of ErbB2 signaling and results in greater antitumor activity in ErbB2-overexpressing breast tumor models." (PMID 26999718, 2016). "Approximately 20–25 % of breast tumours display overexpression of human epidermal growth factor receptor 2 (HER2, ERBB2)." (PMID 27034617, 2016). "Analysis of breast tumours using phospho-specific growth factor receptor antibodies revealed that erbB-2/Her-2 overexpressing tumours are ER/PR-negative, indicating that increased Her-2 receptor is associated with the ER-negative phenotype." (PMID 27884978, 2016). "Nonetheless, these results suggest that nucleolin can be used as a novel target in development of anti-cancer treatments for ErbB2-positive breast tumors." (PMID 27542246, 2016). "The ErbB2 (or HER2) receptor is overexpressed in 25 % of breast tumors and is a major drug target in cancer therapy." (PMID 27596216, 2016). "As expected, the mice with a good prognosis were characterized by low levels of ErbB2 in breast tumors but, surprisingly, also with high levels of pERK1/2 and pAKT in both tumors and liver." (PMID 25853295, 2015). "This correlates with overexpression of ERBB2 due to copy-number amplification and lower expression of subregion 2 genes in MDAMB361, and with the lower expression of cluster 1 RER regions like 16p11.2 in ERBB2 breast tumors." (PMID 26235388, 2015). "The fact that pERK1/2 and pAKT were increased in both breast tumors and livers from mice with long-latency disease would indicate that mice with naturally higher levels of pAKT and pERK1/2 would be more resistant to developing breast tumors induced by ERBB2." (PMID 25853295, 2015). "Overexpression of ErbB2 (HER2), for example, is associated with a highly aggressive breast tumors and poor clinical outcome." (PMID 26084289, 2015). "Our analysis of RER gene expression demonstrates that the breast tumors of the ERBB2 subtype have lower expression levels of cluster 1 RER regions." (PMID 26235388, 2015). "Levels of activated pAKT and pERK1/2 in breast tumors would be determined by two main mechanisms: signaling from the ERBB2 oncoprotein itself, and signaling from other receptors and pathways normally present in the cell." (PMID 25853295, 2015). "A significant correlation between expression of PTK6 and ERBB2 (HER2) has been reported in breast tumors." (PMID 26247733, 2015).
breast tumors (continued). "For example, the proto-oncogene KRAS is found mutated in ~42 % of colorectal tumors but in less than 1 % of breast tumors; whereas amplification of ERBB2 is found in ~13 % of breast tumors but in only ~3 % of colorectal tumors." (PMID 26429708, 2015). "Coamplification and overexpression of PTK6 and ERBB2 was detected in a dataset of 113 Norwegian breast tumors." (PMID 25153721, 2014). "The role of the orphan receptor ErbB-2 in dysregulation of the ErbB network is of major interest, due to its overexpression in 10-20% of breast tumours, diagnosed as HER2-positive." (PMID 24970389, 2014). "Earlier studies have already shown that flotillin-2 is up-regulated in ErbB2 overexpressing breast tumor biopsies." (PMID 24709906, 2014). "This dependence or ‘addiction’ to CUL4A for maintenance of the malignant phenotype and cell survival of CUL4A-overexpressing cells would be similar to that observed in breast tumor cells that overexpress ERBB2 or C-MYC." (PMID 24870930, 2014). "It is estimated that approximately 20%–30% of ErbB2-positive primary breast tumors express the truncated ErbB2." (PMID 24709902, 2014). "In a recent study, we have validated the variants predicted by the eSNV-Detect method with high accuracy in ERBB2 overexpressed (HER2+) breast tumors and adjacent normal tissues using Sanger sequencing." (PMID 25352556, 2014). "We show for the first time that a concomitant high expression of MBP-1 and HDAC1 inversely correlates with ERBB2 expression in primary breast tumors." (PMID 23421821, 2013). "Consistent with previously established roles for LKB1, deletion of LKB1 led to decreased AMPK signaling and increased mTORC1 signaling in ErbB2-positive breast tumors." (PMID 24280377, 2013). "Loss or silencing of LKB1 promotes a switch to the Warburg effect and pro-growth metabolic program to support increased bioenergetic and biosynthetic demand during ErbB2-mediated breast tumor initiation and progression." (PMID 24280377, 2013). "During the in silico simulation, all combination inhibtions except three combination inhibitions (COX-2+ERBB2 for breast tumor, COX-2+ERBB3 for breast tumor and COX-2+EPHA for colon tumor), do not have any effect on the metastasis." (PMID 23967306, 2013). "Tamoxifen-resistant breast tumors are characterized by elevated ERBB2 levels, and ER-positive cell line models overexpressing ERBB2 acquire resistance to tamoxifen." (PMID 23192763, 2013). "To address this question, we created a genetically engineered mouse model to assess the impact of LKB1 deletion on the development and progression of breast tumors driven by the ErbB2 oncogene." (PMID 24280377, 2013). "The human epidermal growth factor receptor 2 (HER2 or ErbB2) is over-expressed in several cancers, in particular in about 30% of breast tumors and is indicative of a poor prognosis for these patients." (PMID 23527120, 2013). "Herceptin binds to the extracellular domain of ERBB2 and is used routinely in the treatment of patients with ERBB2 positive breast tumors." (PMID 24195083, 2013). "The diminished lung metastatic burden in animals with LKB1-null ErbB2 breast tumors raises interesting questions regarding the fitness of LKB1-deficient tumor cells." (PMID 24280377, 2013). "The technology for FISH is very well established for diagnosis of ERBB2 amplification in sporadic breast tumors." (PMID 23284877, 2012). "We extended TMI-1 inhibition tests to a panel of breast tumor cell lines representative of the different molecular subtypes (basal, ERBB2 and luminal)." (PMID 23028451, 2012). "The biological relevance of nuclear ErbB-2/HER2 (NuclErbB-2) presence in breast tumors remains unexplored." (PMID 22356700, 2012). "Its aberrantly reduced protein expression was reported in 3% of breast tumors (predominantly ER/PR/ERBB2 triple-negative and higher-grade familial breast tumors)." (PMID 23181716, 2012).
breast tumors (continued). "Because ERBB2 amplification occurs in 10% to 20% of breast tumors in all three major populations, the haplotype should likely be a common one in all populations." (PMID 23181561, 2012). "We revealed that in HR+breast tumors, PR co-opts ErbB-2 function not only as membrane tyrosine kinase but also as transcriptional regulator." (PMID 22356700, 2012). "Strong support to this possibility is provided by our findings that abrogation of ErbB-2 nuclear localization inhibits in vitro and in vivo growth of breast tumors expressing both NuclErbB-2 and MembErbB-2." (PMID 22356700, 2012). "Previous studies have shown that breast tumors can be divided into five subgroups (Luminal A, Luminal B, Normal-like, ErbB2 over-expressing, and Basal-like) based on their mRNA expression patterns." (PMID 22616941, 2012). "TMI-1 is thus a potent selective inhibitor for breast tumor cells of basal, ERBB2 and luminal molecular subtypes." (PMID 23028451, 2012). "Amplification of the ERBB2 gene in breast tumors is potentially initiated by a complex region that has unusual genomic features and thus requires rigorous, labor-intensive investigation." (PMID 23181561, 2012). "miRNA signatures predict ER, PR and human epidermal growth factor receptor 2 (ErbB-2/neu) status in breast tumors, suggesting that differences in miRNAs are related to hormone-receptor expression." (PMID 22583478, 2012). "TMI-1 was active on triple negative (TN) and ERBB2-overexpressing breast tumor cell lines, and was also highly efficient on human and murine “primary” ERBB2-overexpressing cells." (PMID 23028451, 2012). "After subtracting ER+/PR+ and erbB2+ breast tumors, there remains a miscellaneous collection of so-called “triple negative” tumors (15–20% of total tumors) that are ill defined with respect to their molecular and cellular basis." (PMID 22347416, 2012). "We conducted polymerase chain reaction (PCR)-based assays for primary breast tumors and analyzed publically available array-comparative genomic hybridization data to map a common copy-number breakpoint in ERBB2-amplified primary breast tumors." (PMID 23181561, 2012). "In this study, we described a common copy-number breakpoint that potentially initiates ERBB2 amplification in primary breast tumors." (PMID 23181561, 2012). "When performing a supervised analysis, we were able to identify sets of specific miRNAs for each molecular subtype, except for the ErbB2+ breast tumor samples." (PMID 22353773, 2012). "Amplification of HER2 (ERBB2) occurs in approximately 15 to 25% of human breast tumors and defines a clinically unique subgroup of breast tumors." (PMID 21672245, 2011). "In summary our findings demonstrate that small gene signatures can be identified in patient breast tumor gene expression profiles that accurately predict ER, PR and ERBB2 status." (PMID 22022496, 2011). "It is known that at least 50% of ER-/AR+ breast tumors have ErbB2 overexpression, and anti-ErbB2 treatment is an established part of management for this subgroup." (PMID 21457548, 2011). "Our findings demonstrate that gene signatures can be identified which reliably predict the expression status of the estrogen and progesterone hormone receptors and that of ERBB2 in publically available gene expression profiles of breast tumor samples." (PMID 22022496, 2011). "In conclusion, our findings suggest for the first time that the benefit of using a combination of trastuzumab plus a GSI is prevention of ErbB-2-positive breast tumour recurrence." (PMID 21847123, 2011). "We used 8 independent datasets of human breast tumor samples to define gene expression signatures comprising 24, 51 and 14 genes predictive of ER, PR and ERBB2 status respectively." (PMID 22022496, 2011). "A single probe set representative of each gene was informative to establish ER, PR and ERBB2 expression in breast tumor samples." (PMID 22022496, 2011).
breast tumors (continued). "Attempts to use gene expression profiles to identify the ER, PR and ERBB2 status of human breast tumors have also been reported." (PMID 22022496, 2011). "Here we used 8 independent datasets containing human breast tumor samples profiled on Affymetrix GeneChips to define gene expression signatures predictive of their ER and PR status as well as that of ERBB2." (PMID 22022496, 2011). "Means have also been established for statistical thresholds for ESR1, PR and ERBB2 transcript levels to assign their expression status in profiled breast tumor samples." (PMID 22022496, 2011). "These signatures, as demonstrated by sensitivity and specificity measures, reliably identified hormone receptor and ERBB2 expression in breast tumors that had been previously determined using protein and DNA based assays." (PMID 22022496, 2011). "Gene expression profiling has identified five molecular breast tumor subtypes: luminal A, luminal B, normal breast-like, human epidermal growth factor 2 (HER2/ERBB2) positive, and basal-like." (PMID 21118481, 2010). "Following we examined the Estrogen Receptor alpha-α status depending on nuclear KLF6 distribution and ERBB2-overexpression in ductal breast tumor tissues." (PMID 20126619, 2010). "Both panels detected significant differential ERBB2 gene expression between HER2+ and HER2- breast tumors, and the HER2 gene was the most differentially expressed gene for both panels." (PMID 21172013, 2010). "Nuclear localization of KLF6 observed in cells of breast tumor tissue sections is in line with high expression levels of ERBB2." (PMID 20126619, 2010). "Most importantly, the data provide in vivo evidence that htid is a potential modulator of ErbB-2 signalling in both breast and non-breast tumors over expressing the kinase." (PMID 20565727, 2010). "Within ductal breast tumors, the percentage of ERBB2 overexpressing tissues was almost maintained to those determined for the whole breast tumors population." (PMID 20126619, 2010). "KLF6 is preferentially expressed in 91% (10/11) of small ERBB2 overexpressing ductal breast tumors, while the expression percentage is homogeneous in the remaining tumor size subpopulation." (PMID 20126619, 2010). "Nuclear localization of KLF6 together with an ERBB2-overexpression suggests that KLF6 function is associated with the malignant phenotype, grow and development of this type of breast tumor." (PMID 20126619, 2010). "The human breast cell line (C5.2) and a pool of 5 ERBB2 over-expressing breast tumor samples were used independently for the construction of two AS-enriched libraries." (PMID 21210970, 2010). "Overall these observations clearly suggest that the nuclear expression of KLF6 frequently occurs in ERBB2-overexpressing ductal breast tumor cases, which is in line with tumor aggressiveness." (PMID 20126619, 2010). "ErbB2-overexpressing breast tumors are characterized by very aggressive clinical courses and decreased survival rates, mostly due to the poorly differentiated, highly proliferative and highly invasive nature of their constituent cells." (PMID 20649976, 2010). "In focus on the ERBB2-positive ductal breast tumor population, the results presented in this work demonstrated that there is a significant percentage of tissues that express nuclear KLF6." (PMID 20126619, 2010). "In this sense, nuclear distribution of KLF6 was observed in 100% (7/7) in ERBB2 overexpressing ductal breast tumors with histological grade 1." (PMID 20126619, 2010). "Our results demonstrate that, in spontaneously aroused ErbB2-overexpressing breast tumors, cannabinoids inhibit tumor generation, growth, vascularization, and metastasis." (PMID 20649976, 2010).